KDM7A (lysine demethylase 7A)
Diseases named in the same sentence as KDM7A in open-access papers (continued):
Sharing a sentence is not in itself a finding about the gene and the disease.
T-cell lymphoma (1 paper, 2019). "Furthermore, we have shown these cell lines to bear several characteristics which are typical for this type of T-cell lymphoma including the rearranged chromosome i(7q) and specific mutations in HIST1H3B, KDM7A, SETD2 and STAT5B." (PMID 31143370, 2019).
tumor (16 papers, 2015 to 2026). "A larger tumour size, lymph node metastasis, high miR-451a expression and high KDM7A expression were recognized as risk factors with considerably high OR values." (PMID 38943031, 2024). "Amongst the novel BMP4 targets identified were the transcript encoding the dual histone demethylase, KDM7A, previously shown to promote tumour growth and mediate androgen receptor activity, and FGF4; both were upregulated in both cell lines following BMP4 stimulation." (PMID 37048077, 2023). "In addition, Kdm7a is highly induced in cancer cells in response to nutrient starvation and is associated with tumor suppression, by modulating tumor angiogenesis." (PMID 33257809, 2020). "The tumours were sectioned, and H&E staining, Ki-67 staining, and KDM7A immunohistochemistry (IHC) were performed." (PMID 38943031, 2024). "Reduced KDM7A expression decreased the resistance of CAL27_CTX cells to cetuximab and decreased cell proliferation, migration and tumour growth." (PMID 38943031, 2024). "Consistently, when the mice were sacrificed, it was discovered that tumor weight was significantly smaller in mice receiving the inoculation of KDM7A-depleted cells than the control cells." (PMID 34249916, 2021). "Most importantly, the KDM7A protein level increased in tumor tissues compared to matching normal tissues." (PMID 32781788, 2020). "In the prostate study, we found that the KDM7A inhibitor TC-E 5002 effectively reduced tumor cell growth and migration in vitro." (PMID 32781788, 2020). "Moreover, a significantly lower survival probability of groups with high expression of JHDM1D/KDM7A gene, which showed potential prognostic value in predicting tumor grade in our study, was also observed (Cox p-value = 0.00217)." (PMID 39136575, 2024). "In addition, we found that the interaction network involving JHDM1D/KDM7A was associated with RAF1, ARAF, JAK2, and CAMK2 activation, reinforcing the involvement of JHDM1D/KDM7A in tumor aggressiveness and progression." (PMID 39136575, 2024). "Receiver operating characteristics (ROC) curve analyses showed that combined JHDM1D/KDM7A gene and RP11-363E7.4 lncRNA predicted tumor grade with an AUC of 0.826 (p = 0.004), showing excellent discrimination capacity." (PMID 39136575, 2024). "In the KDM7 family, KDM7A and KDM7B promote the formation of cancer; interestingly, KDM7C/PHF2 inhibits tumor development." (PMID 37218871, 2023). "However, it is largely unknown how KDM7A suppresses tumor progression." (PMID 26688070, 2015). "Although the amplification of tumor volume was not altered by KDM7A knockdown early on following the inoculation, it was significantly slowed toward the end." (PMID 34249916, 2021). "The control tumor was positive for Ki-67, while the KDM7A knock-down tumor was found to be negative." (PMID 32781788, 2020). "The expression of vascular endothelial growth factor (VEGF) was detected in control tumor, but not in KDM7A knock-down tumors." (PMID 32781788, 2020). "Upon quantification of the signal from Western blot for KDM7A and its comparison with the tumor stages, the results were not statistically significant, which might be due to the small sample size." (PMID 32781788, 2020). "In this study we show that the microRNA hsa-miR-137 (miR137) tumor suppressor regulates expression of an extended network of transcriptional coregulators including KDM1A/LSD1/AOF1, KDM2A/JHDM1A/FBXL11, KDM4A/JMJD2A, KDM5B JARID1B/PLU1, KDM7A/JHDM1D/PHF8, MED1/TRAP220/DRIP205 and NCoA2/SRC2/TIF2." (PMID 26461474, 2015).
cancer (10 papers, 2016 to 2026). A tumor composed of atypical neoplastic, often pleomorphic cells that invade other tissues. "The KDM7A (lysine demethylase 7A) gene functions in post-translational modification and has been linked to cancer development and inflammatory responses." (PMID 39273692, 2024). "By exploiting commercially available pharmacological inhibitors, we demonstrate that in AR-positive CRPC cell lines, combinatory inhibition of KDM1A and KDM7A leads to a loss of AR and the AR-driven transcriptome, which in turn attenuates cancer-promoting cell phenotypes." (PMID 41870972, 2026). "KDM7A has been identified as a cancer-promoting factor in many cancers; however, its role in PCa remains largely unexplored." (PMID 41870972, 2026). "Previous studies have shown that KDM7A regulates bone development, adipogenesis, inflammation, as well as the development of various types of cancers." (PMID 32781788, 2020). "Histone demethylase KDM7A regulates many biological processes, including differentiation, development, and the growth of several cancer cells." (PMID 32781788, 2020). "Based on our results, it is possible that KDM7A controls AR activity as an epigenetic co-activator during cancer progression." (PMID 32781788, 2020). "Since AR is known to inhibit apoptosis induced by cytotoxic stimuli, we measured the levels of apoptotic proteins in KDM7A knock-down cells treated with the anti-cancer drug cisplatin." (PMID 32781788, 2020). "The existence of a KDM7A chemical inhibitor further highlighted the value of this data, owing to its clinical application as an anti-cancer drug." (PMID 32781788, 2020). "Therefore, it would be interesting to study the function of KDM7A in other differentiated cancer cells." (PMID 32781788, 2020). "Finally, we investigated the involvement of cellular signaling pathways involved in the anti-cancer effect of AR and/or KDM7A inhibitors on CR-T24 cells." (PMID 32781788, 2020). "Whether H3K27 demethylases including KDM6A, KDM6B and KDM7A play an oncogenic or anti-oncogenic role in cancers is under active investigation." (PMID 28717873, 2018). "Our transcriptome sequencing results demonstrated that Kdm7a knockdown significantly affected the VEGF signaling pathway and cancer‐related pathways, consistent with previous studies." (PMID 39836528, 2025). "In addition, KDM7A is sensitive to 2-hydroxyglutarate (2-HG), an onco-metabolite produced by the mutant isocitrate dehydrogenase 1 (IDH) or IDH2, suggesting an anti-cancer role." (PMID 28717873, 2018). "However, the correlation of KDM7A expression level with each cancer stage was not statistically significant, perhaps due to the small number of cases for each stage." (PMID 32781788, 2020). "Nonetheless, the fact that we identified a correlation between high KDM7A mRNA levels and cancer-dependent deaths only in men, but not in women, may explain the AR dependency of this effect." (PMID 32781788, 2020).
neurological diseases (1 paper, 2023). "In particular, the expression of immediate early genes (IEGs), a series of genes maintaining the function of the nervous system and associating with neurological disorders, are significantly decreased upon Kdm7a knockdown." (PMID 37565374, 2023). "We explored the role of KDM7A in the mammalian nervous system, partially elucidated the relevant regulatory mechanisms, and provided insights for research community of neurological diseases." (PMID 37565374, 2023). "Collectively, the study reveals that KDM7A affects neuron functions by regulating IEGs, which may provide new clues for understanding epigenetic mechanisms in neurological disorders." (PMID 37565374, 2023).
KDM7A also shares sentences with these, for which no sentence is quoted: Obesity (2 papers); Alzheimer disease (1); bone disorder (1); breast tumor (1); colorectal cancer (1); diabetes (1); diabetic nephropathy (1); head and neck squamous cell carcinoma (1); immune diseases (1); lung carcinoma (1); lupus (1); medulloblastoma (1); metabolic disorders (1); metastasis (1); Parkinson disease (1); promyelocytic leukemia (1).